CD40 (CD40 molecule)
Diseases named in the same sentence as CD40 in open-access papers (continued):
Sharing a sentence is not in itself a finding about the gene and the disease.
Burkitt lymphoma (6 papers, 2003 to 2020). A rare form of malignant mature B-cell non-Hodgkin lymphoma. "LMP1, a functional CD40 ortholog encoded by EBV, is both IL-10 responsive and induces secretion of cellular IL-10 in stimulated Burkitt's lymphoma cells." (PMID 18389062, 2008). "Furthermore, the strength of CD40 ligation by CD40L can influence the signalling outcome, with strong CD40 ligation enhancing antigen processing and presentation in Burkitt’s lymphoma cells, compared to weak CD40 ligation." (PMID 31941968, 2020). "Interestingly, CD40 ligation is insufficient in inducing CD226 expression in proliferating B cells, while the viral homologue of CD40, LMP1, sufficiently induces CD226 in the non-EBV Burkitt’s lymphoma line, BL41." (PMID 29202043, 2017).
Hepatitis (6 papers, 2013 to 2025). Inflammation of the liver. "As a downside to this homologous approach, repeated CD40/CD40L stimulation increases the risk for systemic side effects, including hepatitis." (PMID 39741195, 2025). "In this study, we report the extent of tissue inflammation and metabolic alterations during CD40-mediated hepatitis as related to the TNF-α pathway in wt and TNFR1−/− mice in our established model of SBS." (PMID 34440067, 2021). "TNF-α is also involved in the pathophysiology of hepatitis, also upon CD40 activation, including our own SBS model." (PMID 34440067, 2021). "Nevertheless, anti-CD40 mAb-activation has not been applied so far to systematically address the CD40 mAb-mediated hepatitis in mice devoid of the TNFR1 signaling pathway in comparison with their wild type (wt) littermates." (PMID 34440067, 2021). "Mice treated with SnMP, but not those treated with saline, were protected from anti-CD40 induced hepatitis, as reflected by the significantly lower plasma transaminase levels." (PMID 34054870, 2021). "To assess whether the activation status of DCs was altered in the absence of CD160, we measured the levels of multiple ligands on DCs, including CD1d, CD40, CD80, CD95, PD-L1, and HVEM, during α-GalCer-induced hepatitis." (PMID 31332204, 2019).
lymph node metastasis (6 papers, 2011 to 2023). "A lower death risk in negative CD40 mutant cases was observed comparing with positive CD40 mutant cases after sex, age, depth of tumor invasion, and lymph node metastasis were adjusted (HR = 0.383, 95% CI 0.227-0.646, P <0.001)." (PMID 24885116, 2014). "Several studies found that CD40 expression was significantly correlated with lymph node metastasis and distant metastasis as well as TNM stage, meanwhile patients with positive CD40 mutant expression had a poorer prognosis." (PMID 24885116, 2014). "We examined the correlation of the expression of CD40/CD40L, IL12, and IFN-γ with lymph node metastasis and prognosis using TCGA cohort data." (PMID 34209347, 2021). "In addition, we observed that Cluster of differentiation 40 (CD40, p = 0.017), C–C motif chemokine 16 (CCL16, p = 0.019) and IL-6 (p = 0.021) were highly secreted from PDS MCF7-cultures from patients with lymph node metastasis." (PMID 34090457, 2021). "Although no statistical correlation between the expression of CD40/CD40L, IL12, and IFN-γ and lymph node metastasis, CD40L and IFN-γ were statistically correlated with good prognosis." (PMID 34209347, 2021).
osteoporosis (6 papers, 2017 to 2025). A condition of reduced bone mass, with decreased cortical thickness and a decrease in the number and size of the trabeculae of cancellous bone (but normal chemical composition), resulting in increased fracture incidence. "CD40L binds to CD40, is involved in bone metabolism, and leads to an increased risk of osteoporosis in women." (PMID 40671914, 2025). "In this study, we identified and extensively discussed the complex causal role of B cells in osteoporosis, whereas Cao’s study focused on the correlation between the CD40/CD40L system and bone metabolism." (PMID 39086903, 2024). "Our findings may provide some clues for an explanation of the dual mechanism for the CD40/CD40L system involved in osteoporosis development." (PMID 36341399, 2022).
sarcoidosis (6 papers, 2012 to 2025). Sarcoidosis is a multisystemic disorder of unknown cause characterized by the formation of immune granulomas in involved organs. "For example, CD40 which is required to activate APCs, is expressed in higher levels on AMs in patients with sarcoidosis." (PMID 33324666, 2020). "Some EV markers were common between HP and sarcoidosis (CD11c, CD1c, CD209, CD4, CD40, CD44, CD8)." (PMID 36835481, 2023).
Sjögren’s syndrome (6 papers, 2009 to 2026). "Interestingly, splenic MDSCs of mice in early stage of experimental Sjögren’s syndrome (10 days postimmunization) showed an immature phenotype (low expression levels of CD40, CD80, CD86 and MHC-II markers) and potent suppressive activity of T cell proliferation." (PMID 38495880, 2024). "Iscalimab, a CD40-targeted antagonist, is undergoing multiple clinical trials in SLE and Sjögren’s syndrome." (PMID 40211396, 2025). "CFZ533, a humanized anti-CD40 IgG1 mAb with a modified Fc portion resulting in a lack of Fcγ-dependent effects, was examined in a phase IIa randomized trial for patients with Sjögren’s syndrome." (PMID 31426619, 2019).
tuberculosis (6 papers, 2010 to 2024). A chronic, recurrent infection caused by the bacterium Mycobacterium tuberculosis. "Engaging CD40 on dendritic cells using the CD40 agonist significantly enhanced the antigen-specific Th17 response in mice, which means that the CD40–CD154 pathway plays a key role in adaptive immune response against tuberculosis." (PMID 35463641, 2022).
acute coronary syndrome (5 papers, 2011 to 2023). Signs and symptoms related to acute ischemia of the myocardium secondary to coronary artery disease. "The genetic variants of CD40 gene may influence the efficiency of CD40 gene translation and may determine an individual's susceptibility on acute coronary syndrome." (PMID 27200368, 2016). "The interaction of CD40–CD40ligand (hereafter CD40l) is believed to play a pivotal role in acute coronary syndrome." (PMID 37808562, 2023). "Acute coronary syndrome (ACS) can be triggered by the presence of inflammatory factors which promote the activation of immune cells by costimulatory molecules such as CD40 and its ligand CD40L." (PMID 31183392, 2019). "Studies had reported the relationship between rs1883832 at CD40 locus and acute coronary syndrome." (PMID 27200368, 2016).
esophageal squamous cell carcinoma (5 papers, 2019 to 2025). Esophageal squamous cell carcinoma (ESCC) is a type of esophageal carcinoma (EC) that can affect any part of the esophagus, but is usually located in the upper or middle third. "CD40 expression on esophageal squamous cell carcinoma (ESCC) leads to the progression of cancer and metastasis to lymph nodes." (PMID 32902664, 2021). "In a study of phase III and IV of esophageal squamous cell carcinomas, the survival rate of CD40+ tumor patients was significantly lower compared with CD40– tumor patients." (PMID 31708918, 2019). "Finally, CD40 is present on the surface of various epithelial tumor cells, including both gastric adenocarcinomas and esophageal squamous cell carcinomas, suggesting an additional mechanism of action of CD40 agonists via direct induction of tumor cell apoptosis." (PMID 39907035, 2025).
follicular lymphoma (5 papers, 2017 to 2026). Follicular lymphoma is a form of non-Hodgkin lymphoma characterized by a proliferation of B cells whose nodular structure of follicular architecture is preserved. "according to which follicular lymphoma patients and healthy controls with TT genotypes had decreased plasma circulating soluble CD40 as well as CD40 cell surface expression in dendritic cells from healthy individuals compared to CC homozygotes." (PMID 34604057, 2021). "For instance, in conditions such as follicular lymphoma, CD40 signaling promotes survival rather than cell death." (PMID 40397730, 2025).
Hodgkins lymphoma (5 papers, 2011 to 2025). A heterogeneous group of malignant lymphoid neoplasms of B-cell origin characterized histologically by the presence of Hodgkin and Reed-Sternberg (HRS) cells in the vast majority of cases. "However, studies have implicated gene variants in the IκBε/c-Rel pathway in tumorigenesis: mutations in CD40, c-Rel and IκBε are associated with Hodgkin's Disease, a malignant transformation of germinal centre B cells." (PMID 21915344, 2011). "Also, CCL5 secretion is increased when CD40 is cocultured with classical Hodgkin lymphoma cells or with MSCs derived from lymph nodes of Hodgkin lymphoma patients." (PMID 35702353, 2022). "Our findings exhibited significant correlations in Hodgkin's lymphoma between CD247, CMTM6, CD25, ENTPD1, MBL2, and CD40." (PMID 40360443, 2025).
mantle cell lymphoma (5 papers, 2015 to 2023). Mantle cell lymphoma is a rare form of malignant non-Hodgkin lymphoma affecting B lymphocytes in the lymph nodes in a region called the ``mantle zone''. "It has also been suggested that dysregulation of two proteins, IL4 and CD40, leads to dysfunction of cell proliferation in mantle cell lymphoma, and dysregulation of MIR381 leads to dysfunction of proliferation in esophageal cancer." (PMID 26897165, 2016). "CD40 is expressed in mature B cells, including mantle cell lymphoma cells." (PMID 29907126, 2018).
myocardial infarction (5 papers, 2011 to 2024). Gross necrosis of the myocardium, as a result of interruption of the blood supply to the area, as in coronary thrombosis. "Post-myocardial infarction cDCs upregulate CCR7 (the chemokine receptor required for lymph node migration) and CD40 expression; specific activation of the cDC2 subset induces CD86 expression as well as CD4+ T cell proliferation and accompanies IFN-γ and IL-17 production." (PMID 31681306, 2019). "In genetic terms, the causality found may be due to alterations in Human Leukocyte Antigen (HLA), CD40, and PINK1/Parkin genes in patients with MS and PD, which modulate the body’s immune-inflammatory response and mitochondrial autophagy, thereby influencing the occurrence of myocardial infarction." (PMID 38850523, 2024).
myocardial ischemia (5 papers, 2011 to 2025). A disorder of cardiac function caused by insufficient blood flow to the muscle tissue of the heart. "According to available scientific data, miR-145-5p can act as a “cardioprotective” molecule in patients with myocardial ischemia and, through the negative regulation of CD40, is involved in reducing the activity of the inflammatory response and apoptosis caused by hypoxia." (PMID 39684689, 2024). "CD154, a marker of cardiac ischemia and the ligand of CD40, was often elevated in septic patients." (PMID 33986658, 2020). "In conclusion, the present study shows that BYHWD has a protective effect against ISO-induced myocardial ischemia, and this effect may be attributed to the down-regulation of CD40 and CD40L expressions." (PMID 21792360, 2011). "Moreover, our previous research reported that GC, a specific CD40 inhibitor, could exhibit significant protective effect of myocardial ischemia and reperfusion injury via suppressing the CD40/NF-κB signal pathway." (PMID 35707280, 2022). "In the present study, we found that the ISO-induced myocardial ischemic rats presented a high level of CD40 and CD40L expressions, compared with the control group, indicating that myocardial ischemia is related to CD40/CD40L inflammatory pathway." (PMID 21792360, 2011). "Our data suggest that the roles of BYHWD are not only related to its antioxidative action and regulation of lipid metabolisms, but also to the inhibition of inflammatory pathway by the decreased CD40 and CD40L expressions in rats with myocardial ischemia." (PMID 21792360, 2011).
nephritis (5 papers, 2008 to 2022). Inflammation of renal tissue. "Accordingly, we also evaluated the potential association of CD40, BLK and BANK1 with the increased risk of nephritis or GI complications in our study." (PMID 36233442, 2022). "Early studies in SLE murine models suggested that blocking the interaction between CD40 and CD154 reduced nephritis and anti-dsDNA antibodies, leading to improved survival." (PMID 18786258, 2008).
prostate tumors (5 papers, 2009 to 2024). "Strategies investigated include the use of smart immunogenic biomaterials (IBM) loaded with anti-CD40 in different tumor types including immunologically cold tumors like pancreatic and prostate tumors." (PMID 34765538, 2021). "In the TRAMP-C2 prostate tumor model the combination of IL-15 with agonistic anti-CD40 produced additive effects in terms of numbers of TRAMP-C2 tumor specific Spas/SCNC/9H tetramer positive CD8 T cells expressed and tumor responses." (PMID 32508818, 2020). "In the TRAMP-C model of spontaneous prostate tumor formation, the simple addition of the chemical crosslinker that only activated CD40 downstream pathways in dendritic cells was sufficient to lead to tumor eradication." (PMID 19812695, 2009). "Multiple representative differentially methylated regions (DMRs), including immune‐related genes, such as CD40, Galectin3, OX40L, and STING, were detected in prostate tumors when compared to adjacent normal tissues." (PMID 39162297, 2024). "Additionally, immune-based pathways that include genes crucial for the proliferation of lymphoid and T-cell progenitors, such as CD40 and CD226, were enriched in prostate tumors from AA men." (PMID 38566104, 2024).
acute lung injury (4 papers, 2021 to 2025). A condition of lung damage that is characterized by bilateral pulmonary infiltrates (pulmonary edema) rich in neutrophils, and in the absence of clinical heart failure. "Previous studies found that soluble CD40 ligands accumulated in stored blood components and activated neutrophils through CD40, potentially affecting transfusion-related acute lung injury." (PMID 40027123, 2025). "This CD40/CD40L complex may be a major target in a transfusion-related acute lung injury prevention strategy." (PMID 35740005, 2022). "Inhibition of the neutrophil-platelet CD40/CD40L axis with anti-CD40 Ab is reported to significantly reduce pulmonary edema and platelet activation and reduce neutrophil recruitment to the lungs in a mouse model of transfusion-related acute lung injury." (PMID 33986193, 2021).
amyotrophic lateral sclerosis (4 papers, 2019 to 2024). Amyotrophic lateral sclerosis (ALS) is a neurodegenerative disease characterized by progressive muscular paralysis reflecting degeneration of motor neurons in the primary motor cortex, corticospinal tracts, brainstem and spinal cord. "The activation of CD40L/CD40 has also been shown to occur in individuals with amyotrophic lateral sclerosis (ALS) as well as in animal models of ALS." (PMID 39480764, 2024). "For example, astrocytes acquire CD40 expression after incubation with IFN-γ, neural tissue injury or in a transgenic mouse model of amyotrophic lateral sclerosis, a disease driven by CD40." (PMID 31921199, 2019). "In amyotrophic lateral sclerosis (ALS) and multiple sclerosis (MS) patients, intrathecal or IV BM-MSC injection increased Treg numbers, reduced lymphocyte proliferation and downregulated the expression of activation and maturation markers such as CD40, CD83 and HLA-DR on DCs." (PMID 32595362, 2020).
Cirrhosis (4 papers, 2016 to 2022). A chronic disorder of the liver in which liver tissue becomes scarred and is partially replaced by regenerative nodules and fibrotic tissue resulting in loss of liver function. "CD14 selection has no appreciable adverse effect on function such as response to TLR ligation or CD40 ligation and yielded cells efficient at reversing cirrhosis in experimental models." (PMID 28673774, 2017).
colon adenocarcinoma (4 papers, 2020 to 2023). "We selected the MC38 colon adenocarcinoma model because these tumors are known to be sensitive to anti-CD40 immunotherapy." (PMID 38060331, 2023). "Furthermore, MC38 colon adenocarcinoma–bearing mice with NRF2 constitutively activated in leukocytes were resistant to anti-CD40 immunotherapy." (PMID 38060331, 2023).
eosinophilia (4 papers, 2016 to 2024). "CD40 signalling is important for OVA-induced eosinophilia and the production of IL-4, IL-5, and IL-13 in a mouse model of allergic asthma." (PMID 33976586, 2021).
epilepsy (4 papers, 2021 to 2025). A brain disorder characterized by episodes of abnormally increased neuronal discharge resulting in transient episodes of sensory or motor neurological dysfunction, or psychic dysfunction. "This suggests that CD40-mediated inflammation could contribute to the enhanced neuroexcitability that triggers epilepsy and encourages the exploration of CD40 antagonists in future clinical trials for the treatment of epilepsy." (PMID 35456932, 2022). "In addition, the CD40 molecular signaling may play a role in the development of epilepsy and drug-resistant epilepsy through the activation of P38 MAPK." (PMID 34446808, 2021).
esophageal cancer (4 papers, 2016 to 2025). A primary or metastatic malignant neoplasm involving the esophagus. "CD40 expression was frequently shown to be associated with prolonged survival; however, contrary results were evident in lung and esophageal cancer where CD40 expression correlated with poor prognosis." (PMID 32582531, 2020). "In conclusion, the current study provides compelling evidence for the efficacy of a CD40 agonistic antibody in combination with neoadjuvant chemoradiation in esophageal cancer, highlighting its potential to improve clinical outcomes via enhanced immune responses." (PMID 39907035, 2025).
fibrosarcoma (4 papers, 2008 to 2021). A malignant mesenchymal fibroblastic neoplasm affecting the soft tissue and bone. "In the T241 fibrosarcoma model, increased surface expression of CD86 on cDCs was observed in the tumor draining lymph nodes of mice treated with anti-CD40 mAb alone and in mice treated with anti-CD40 mAb in combination with sunitinib." (PMID 27385210, 2016).
gastric tumor (4 papers, 2014 to 2024). "The levels of CD40 expression were detected on the Gr-1+/CD11b+ MDSCs from gastric tumor-bearing and tumor-free mice." (PMID 25009656, 2014). "In the present study, CD40 was observed to be highly expressed on the MDSCs obtained from mice bearing gastric tumors." (PMID 25009656, 2014). "The results of the current study showed that CD40 is highly expressed on the MDSCs of a gastric tumor model." (PMID 25009656, 2014). "In our previous study, we observed that CD40 was highly expressed in gastric tumor MDSC." (PMID 26462153, 2015). "Therefore, the present study evaluated CD40 expression on the MDSCs of a gastric tumor model, with a focus on the dynamics of tumor progression and CD40 expression on MDSCs." (PMID 25009656, 2014).